CENPE (centromere protein E)
Description:
Microtubule plus-end-directed kinetochore motor which plays an important role in chromosome congression, microtubule-kinetochore conjugation and spindle assembly checkpoint activation. Drives chromosome congression (alignment of chromosomes at the spindle equator resulting in the formation of the metaphase plate) by mediating the lateral sliding of polar chromosomes along spindle microtubules towards the spindle equator and by aiding the establishment and maintenance of connections between kinetochores and spindle microtubules. The transport of pole-proximal chromosomes towards the spindle equator is favored by microtubule tracks that are detyrosinated. Acts as a processive bi-directional tracker of dynamic microtubule tips; after chromosomes have congressed, continues to play an active role at kinetochores, enhancing their links with dynamic microtubule ends. Suppresses chromosome congression in NDC80-depleted cells and contributes positively to congression only when microtubules are stabilized. Plays an important role in the formation of stable attachments between kinetochores and spindle microtubules The stabilization of kinetochore-microtubule attachment also requires CENPE-dependent localization of other proteins to the kinetochore including BUB1B, MAD1 and MAD2. Plays a role in spindle assembly checkpoint activation (SAC) via its interaction with BUB1B resulting in the activation of its kinase activity, which is important for activating SAC. Necessary for the mitotic checkpoint signal at individual kinetochores to prevent aneuploidy due to single chromosome loss (By similarity).
Synonyms: CENP-E; KIF10; PPP1R61; MCPH13
Tractability: Small molecule: a structure with a bound ligand is known; a high-quality ligand is known; it has a binding pocket of medium quality. PROTAC: UniProt records ubiquitination sites on it; ubiquitination databases record sites on it; a small molecule that binds it is known.
Gene: Protein-coding gene on chromosome 4 (103,105,349 to 103,198,463, reverse strand). Ensembl gene ENSG00000138778.
Subcellular location: Chromosome, centromere, kinetochore; Cytoplasm, cytoskeleton, spindle; Chromosome, centromere
Subcellular location (Human Protein Atlas): Microtubules; Cytokinetic bridge; Mitotic spindle
Pathways (Reactome):
Cell Cycle: Amplification of signal from unattached kinetochores via a MAD2 inhibitory signal; EML4 and NUDC in mitotic spindle formation; Mitotic Prometaphase; Resolution of Sister Chromatid Cohesion; Separation of Sister Chromatids
Hemostasis: Kinesins
Immune System: MHC class II antigen presentation
Signal Transduction: RHO GTPases Activate Formins
Vesicle-mediated transport: COPI-dependent Golgi-to-ER retrograde traffic
Gene Ontology:
Molecular function: kinetochore binding; microtubule binding; microtubule motor activity; protein binding; ATP binding
Biological process: attachment of mitotic spindle microtubules to kinetochore; chromosome segregation; kinetochore assembly; lateral attachment of mitotic spindle microtubules to kinetochore; metaphase chromosome alignment; microtubule plus-end directed mitotic chromosome migration; mitotic cell cycle; mitotic chromosome movement towards spindle pole; mitotic metaphase chromosome alignment; mitotic spindle organization; regulation of mitotic metaphase/anaphase transition; microtubule-based movement; attachment of spindle microtubules to kinetochore; spindle organization
Cellular component: chromosome; chromosome, centromeric region; condensed chromosome, centromeric region; kinetochore; kinetochore microtubule; membrane; microtubule; microtubule cytoskeleton; midbody; mitotic spindle; mitotic spindle midzone; nucleus; spindle midzone; cytosol; spindle
Genetic constraint (gnomAD): Loss-of-function variants: 75 observed, 201.37 expected, observed/expected ratio (o/e) 0.37, 90% interval 0.31 to 0.45. The upper end of that interval is the gene's LOEUF score, 0.45, which puts it in group 2 of 6, group 1 being the genes least tolerant of losing a copy. Missense variants: 1,893 observed, 2,122.1 expected, observed/expected ratio (o/e) 0.89, 90% interval 0.86 to 0.93. Synonymous variants: 699 observed, 712.77 expected, observed/expected ratio (o/e) 0.98, 90% interval 0.92 to 1.04.
Gene-disease validity (ClinGen):
ClinGen rates the evidence that CENPE causes each of these diseases.
autosomal recessive primary microcephaly (autosomal recessive): Limited. Autosomal recessive primary microcephaly (MCPH) is a rare genetically heterogeneous disorder of neurogenic brain development characterized by reduced head circumference at birth with no gross anomalies of brain architecture and variable degrees of intellectual impairment.
Homologues: Orthologues: chimpanzee CENPE (97% identical), macaque CENPE (96% identical), rabbit CENPE (79% identical), pig CENPE (76% identical), dog CENPE (66% identical), mouse Cenpe (60% identical), rat Cenpe (59% identical), guinea pig Cenpe (57% identical), zebrafish cenpe (26% identical), Drosophila melanogaster cmet (18% identical), Drosophila melanogaster cana (18% identical). Paralogues in human: KIF21A (13% identical), KIF21B (12% identical), KIF4B (11% identical), KIF27 (11% identical), KIF4A (11% identical), KIF15 (11% identical), KIF7 (11% identical), KIF13B (10% identical), KIF5A (9% identical), KIF13A (9% identical), KIF5C (9% identical), KIF1A (9% identical), and 29 more.
Diseases named in the same sentence as CENPE in open-access papers:
CENPE is named in the same sentence as 78 diseases in open-access papers, as found by Europe PMC text mining. Sharing a sentence is not in itself a finding about the gene and the disease. The quoted sentences say what the papers report.
breast cancer (30 papers, 2011 to 2025). A primary or metastatic malignant neoplasm involving the breast. "This unbiased approach allowed us to identify a panel of five biomarkers, DNMT3B, EXO1, MCM10, CENPF and CENPE, that are robustly and significantly associated with disease-free survival prognosis in breast cancer." (PMID 37592220, 2023). "Further in vitro experiment using high-risk prognostic sensitive drugs under different breast cancer cells showed that upregulated expression of the high-risk related gene CENPE was positively related with the sensitivity of breast cancer cells to (+)-JQ1." (PMID 34745136, 2021). "Previous studies have shown that CENPE was dysregulated in various malignancies, such as epithelial ovarian cancer, prostate cancer, and breast cancer, and overexpression of CENPE was associated with promoting cell cycle progression and tumor cell growth." (PMID 32127012, 2020). "CENPE has been implicated in the progression of cancers such as non‐small cell lung cancer, prostate cancer, and breast cancer; however, research on its role in ccRCC remains limited and our study is among the first to uncover the oncogenic role of CENPE in ccRCC." (PMID 40794013, 2025). "High expression of both CENPE and CENPF was associated with low oestrogen and progesterone receptor expression levels in breast cancer." (PMID 37592220, 2023). "Further in vitro evaluation confirmed that (+)-JQ1 had the best cancer cell selectivity and exerted its anti-breast cancer activity through CENPE." (PMID 34745136, 2021). "Knockdown of CENPE in breast cancer, prostate cancer, and neuroblastoma leads to repression of the tumor proliferation." (PMID 34868981, 2021). "In this study, we examined the relationship between CENPE expression and the anti-breast cancer activity of the selected compounds." (PMID 34745136, 2021). "First, we observed that CENPE mRNA expression level is significantly higher in breast cancer cell lines than that in normal breast epithelial cells." (PMID 34745136, 2021). "CENPE is highly expressed in lung adenocarcinoma (Gao, Wang & Zhang, 2019), breast cancer and esophageal adenocarcinoma." (PMID 31788359, 2019). "In breast cancer, CENPE upregulation was strongly and negatively correlated with disease-specific survival." (PMID 30716092, 2019). "CENPE overexpression was correlated with cyclin B1 expression and is related to poor prognosis in breast cancers." (PMID 26933822, 2016). "Additionally, the expression level of CENPE is notably elevated in the basal subtype of breast cancer relative to other subtypes, and knockdown of CENPE impairs cell viability." (PMID 40794013, 2025). "Recently, Tucker and colleagues discovered that CENPE inhibitors could overcome resistance to microtubule-binding agents like taxanes by exacerbating CIN to induce breast cancer cell death, nominating this combination as a synergistic therapeutic approach." (PMID 40002279, 2025). "On the other hand, upregulation of CENPE has been observed for some breast cancer cells, with a poor prognosis; hence, CENPE could act both as an oncogene and as a tumor suppressor." (PMID 34573304, 2021). "Taken together, our results indicated that (+)-JQ1 might exert its anti-breast cancer activity through CENPE." (PMID 34745136, 2021). "The results showed that CENPE was significantly elevated in breast cancer cell lines." (PMID 34745136, 2021). "The upregulated CENPE has been found to be involved in the tumorigenesis of breast cancer, prostate cancer, neuroblastoma, etc., and CENPE deletion could lead to the apoptosis of tumor cells." (PMID 34868981, 2021). "These up-regulated genes were strongly associated with mitosis and cell cycle control, whereas the down-regulated genes aided in stratifying patients into molecular subtypes, such as BRCA2 (breast cancer 2), CENPE (centromere associated protein E) and CENPF (centromere associated protein F)." (PMID 26110379, 2015).
breast cancer (continued). "Moreover, the overexpressed CENPE was closely related to the poor prognosis in breast cancer (BC), which indicated that CENPE could be a potential prognosis biomarker of BC." (PMID 37925501, 2023). "The result showed that U50A consistently downregulates SMC5, ATRX, CENPE, and CENPF, indicating a widespread phenomenon that these genes are downstream targets of U50A in breast cancer." (PMID 34944924, 2021). "We further examined the mRNA expression level of CENPE in breast epithelial cell line MCF10A and breast cancer cell lines MDA-MB-231 and MCF7." (PMID 34745136, 2021). "We also show that breast cancer cell lines with high mitotic activity are preferentially sensitive to small molecule inhibitors that target mitotic apparatus proteins PLK1, CENPE and AURKB/C, designated GSK462364, GSK923295, and GSK1070916, respectively." (PMID 27368372, 2016). "We measured quantitative dose responses for 53 breast cancer cell lines to inhibitors of PLK1, CENPE and AURKB/C designated GSK462364 GSK923295 and GSK1070916, respectively." (PMID 27368372, 2016). "CCNB1 mRNA expression has been reported to be significantly and positively correlated with mRNA expression levels of CENPE, AURKB, PLK1, and PLK4 in both breast tumors and breast cancer cell lines." (PMID 21445301, 2011). "These analyses revealed five genes, DNMT3B, EXO1, MCM10, CENPF and CENPE, that are normally not expressed in healthy breast tissue but become frequently activated in breast cancers." (PMID 37592220, 2023). "Additionally, CENPE, TOP2A, CENPF, TTK, and NDC80 are highly expressed in the cell cycle of basal-like breast cancer." (PMID 35496042, 2022). "In addition, CENPE and TOP2A are upregulated in a number of solid cancers and are involved in mitotic cell cycle nodes in breast cancer." (PMID 35496042, 2022). "Consistent with this, we have shown that the small molecule inhibitors GSK462364, GSK923295, and GSK1070916 that target the network proteins PLK1, CENPE, and AURKB/C, respectively, inhibit the growth of breast cancer cell lines with high MNAI at lower concentrations than cell lines with low MNAI." (PMID 27368372, 2016). "Unlike CENPE, KIF14 acts as an oncogene in various cancers, including lung cancers, ovarian cancers, breast cancers and adult gliomas." (PMID 26933822, 2016).
lung adenocarcinoma (11 papers, 2019 to 2025). A carcinoma that arises from the lung and is characterized by the presence of malignant glandular epithelial cells. "Another gene following this pattern of expression is CENPE, which is associated with lung adenocarcinoma cell proliferation, and the expression is correlated with poor prognosis in EAC." (PMID 38604503, 2024). "Incidentally, CENPE encodes centromere-associated protein E, which is a human kinetochore protein that promotes lung adenocarcinoma proliferation." (PMID 35814368, 2022). "Meanwhile, CENPE has been found to be involved in the process of mitosis and silence of CENPE greatly blocks lung adenocarcinoma proliferation." (PMID 40794013, 2025). "Previous studies confirmed that CENPE promoted the proliferation of multiple cancers, such as ovarian cancer, lung adenocarcinoma and lung adenocarcinoma." (PMID 37925501, 2023). "Recent studies have confirmed that CENPE is highly expressed in lung adenocarcinoma tissues and promotes lung adenocarcinoma cell proliferation." (PMID 36247089, 2022). "First, CENPE is overexpressed in lung adenocarcinoma and promotes lung cancer cells proliferation, which is regulated by FOXM1." (PMID 34944924, 2021). "In addition, it was found that CENPE was highly expressed in lung adenocarcinoma tissues, the proliferation of lung adenocarcinoma cells was inhibited by suppression of CENPE expression, and the expression of FOXM1 was also directly correlated with the expression of CENPE." (PMID 37335738, 2023).
lung cancer (11 papers, 2016 to 2025). A malignant neoplasm involving the lung. "For instance, CENPE is overexpressed in non‐small cell lung cancer and associated with poor prognosis." (PMID 40794013, 2025). "GSK923295 is a potent and specific allosteric inhibitor of CENPE that has been shown to inhibit cell proliferation in vitro and tumour growth in vivo in lung cancer and several other malignancies." (PMID 40002279, 2025). "In lung cancer models specifically, CENPE inhibition has shown promising synergistic effects when combined with Navitoclax, a BH3-mimetic that inhibits anti-apoptotic proteins, as well as MEK/ERK inhibitors." (PMID 40002279, 2025). "We investigated the impact of inhibiting anti-apoptotic signals with the BH3-mimetic navitoclax in lung cancer cells treated with the selective CENPE inhibitor GSK923295 (mitotic blocker) or the MPS1 inhibitor BAY1217389 (mitotic driver)." (PMID 38258067, 2023). "In vitro studies further determined that the pro-proliferative effect of CENPE expression on lung cancer cells is modulated directly by FOXM1 via binding to the promoter region of CENPE." (PMID 34868981, 2021). "Due to the fact that A549 cells represent a model of NSCLC, the most common lung cancer type, and exhibit elevated protein expression of CENPE and MPS1 compared to the large cell lung cancer model NCI-H460 cells, we selected A549 cells for the subsequent experiments in this study." (PMID 38258067, 2023). "After knocking down the expression of CENPE, the proliferation of lung cancer cells is inhibited." (PMID 35456460, 2022). "The findings align with prior studies that have documented the increased expression of CENPE and MPS1 in lung cancer, underscoring the significance of targeting these proteins." (PMID 38258067, 2023). "The results demonstrated that CENPE and MPS1 mRNA levels, determined by qRT-PCR, were upregulated in both lung cancer cell lines when compared to the non-tumor cell line HPAEpiC." (PMID 38258067, 2023).
ovarian carcinoma (11 papers, 2015 to 2024). A malignant neoplasm originating from the surface ovarian epithelium. "In ovarian cancer cells, changes in CENPE expression following ATAD2 inhibition resulted in cell-cycle arrest and apoptosis induction, which led to the suppression of ovarian cancer growth." (PMID 37479754, 2023). "Our results indicate that CENPE was significantly downregulated in both ovarian cancer cell lines at both the mRNA and protein levels following BAY-850 treatment." (PMID 37479754, 2023). "Based on our results, together with the findings of previous studies and clinical trials, CENPE inhibitors can be rapidly utilized in clinical settings as an effective potential ovarian cancer therapy." (PMID 37479754, 2023). "To examine the role played by CENPE in ovarian cancer growth, we treated ovarian cancer cell lines with GSK923295, a potent CENPE inhibitor with an inhibitory constant (Ki) of 3.2 nM." (PMID 37479754, 2023). "Our study, for the first time, shows that ATAD2 is a promoter of ovarian cancer tumor growth by regulating CENPE expression." (PMID 37479754, 2023). "Finally, we demonstrate that the combined use of both ATAD2 and centromere protein E (CENPE) inhibitors results in a more potent suppressive effect on ovarian cancer growth than the use of either inhibitor alone." (PMID 37479754, 2023). "Furthermore, we observed that the CENPE inhibitor GSK923295 significantly potentiated the tumor-suppressive effects of the ATAD2 inhibitor BAY-850 in ovarian cancer cells." (PMID 37479754, 2023). "Thus, our study identified ATAD2 as regulators of ovarian cancer growth and metastasis that can be targeted either alone or in combination with CENPE inhibitors for effective ovarian cancer therapy." (PMID 37479754, 2023). "Additionally, our results indicate that CENPE inhibitors can be combined with ATAD2 inhibitors for effective ovarian cancer therapy." (PMID 37479754, 2023). "Collectively, our studies illuminate the role of ATAD2 as a facilitator of ovarian cancer growth and metastasis and indicate that ATAD2 inhibitors, used either alone or in combination with CENPE inhibitors, may represent therapeutic option for treating ovarian cancer patients." (PMID 37479754, 2023). "The depletion of CENPE and CENPF has been related to the significant disruption of the cell cycle and paclitaxel resistance in ovarian cancer." (PMID 35496042, 2022). "Our study revealed gene depletion across a number of molecular components involved in the spindle assembly checkpoint and mitotic regulation, including BUB1, CCNB1, CENPE and CENPF in paclitaxel resistant ovarian cancer cell lines." (PMID 29618387, 2018). "Among them, expression of CENPE and CCNB2 correlates with worse clinical outcomes of patients with breast or ovarian cancers." (PMID 26317392, 2015). "Transcriptome-wide mRNA expression profiling of ovarian cancer cells treated with BAY-850 revealed that ATAD2 inhibition predominantly alters the expression of centromere regulatory genes, particularly centromere protein E (CENPE)." (PMID 37479754, 2023). "Pharmacological CENPE inhibition phenotypically recapitulated the cellular changes induced by ATAD2 inhibition, and combined pharmacological inhibition of both ATAD2 and CENPE inhibited ovarian cancer cell growth more potently than inhibition of either alone." (PMID 37479754, 2023).